RBM10 (RNA binding motif protein 10)
Diseases named in the same sentence as RBM10 in open-access papers (continued):
Sharing a sentence is not in itself a finding about the gene and the disease.
lung adenocarcinoma (continued). "As a comparison, we identified alternative splicing events significantly associated with RBM10 mutation in lung adenocarcinoma." (PMID 24498085, 2014). "More recently, in a large sequence analysis of lung adenocarcinomas, RBM10 was found to be frequently mutated and subject to recurrent nonsense, frame-shift or splice-site mutations." (PMID 24000153, 2013). "RBM10 is frequently downregulated in lung, colorectal, pancreatic and endometrial cancers and loss of function mutations have been identified in lung adenocarcinoma." (PMID 39863103, 2025). "However, a report shows that high RBM10 expression and PD-L1 positivity in patients with lung adenocarcinoma are associated with poor outcomes 47, suggesting differential role of RBM10 in the tumorigenesis of different tumours." (PMID 40740233, 2025). "Moreover, low expression of RBM10 was associated with late clinical stage and poor prognosis of lung adenocarcinoma patients." (PMID 34975322, 2022). "RBM10 mutations co-occur with mutations in known lung adenocarcinoma oncogenes (KRAS, EGFR, PIK3CA." (PMID 34065983, 2021). "RBM10 is one of the frequently mutated genes in lung adenocarcinoma (LUAD)." (PMID 34367963, 2021). "In addition, RBM10 mutations are frequently observed in lung adenocarcinomas, colorectal carcinomas, and pancreatic ductal adenocarcinomas." (PMID 32947864, 2020). "Furthermore, RBM10 is mutated in pancreatic intraductal papillary mucinous neoplasms, 7% of lung adenocarcinomas, and 21% of invasive lung adenocarcinomas." (PMID 28662214, 2017). "Considering the similarities between RBM5 and RBM10, and the recent finding that RBM10 is mutated in up to 21% of invasive lung adenocarcinomas, we hypothesized that RBM10 shares RBM5’s tumor-suppressor properties in SCLC." (PMID 28662214, 2017). "However, the functional role of RBM10 in lung adenocarcinoma (LUAD) and the underlying molecular mechanism remains unclear." (PMID 34975322, 2022). "Interestingly, RBM10 mutations have recently been associated with lung adenocarcinoma pathogenesis." (PMID 28662214, 2017). "RBM10 mutations frequently coexist with EGFR mutations, influencing lung adenocarcinoma progression through gene mutation and splicing regulation." (PMID 40740233, 2025). "This study mainly explored the immune regulation mechanism of RBM10 in the development of lung adenocarcinoma and its influence on sensitivity to targeted therapy drugs." (PMID 37509501, 2023). "More truncated and missense somatic mutations of RBM10 have been detected in lung adenocarcinoma in recent studies, but the role of RBM10 in lung adenocarcinoma is unclear." (PMID 37509501, 2023). "A nomogram model of related RBM10 was constructed and showed that it can inhibit the occurrence and development of lung adenocarcinoma." (PMID 37509501, 2023). "The expression level of RBM10 affects the efficacy of targeted drug therapy and the survival prognosis of lung adenocarcinoma patients, which has a certain guiding significance for the clinical treatment of these patients." (PMID 37509501, 2023). "In this study, we obtained sequencing data from the TCGA database of lung adenocarcinoma patients with high expression of RBM10 in order to analyze patient sensitivity to targeted drugs." (PMID 37509501, 2023). "Further verification in the A549 lung adenocarcinoma cell line showed that the mRNA expression level of RBM10 was lower than that of the control group." (PMID 37509501, 2023). "Univariate and multivariate independent analyses of survival and prognosis of lung adenocarcinoma were conducted using the data of the test group and the control group, respectively, and the results of both groups of data included RBM10." (PMID 37509501, 2023). "The qRT-PCR for 20 lung adenocarcinoma tissues showed that the expression of RBM10 in these tissues was significantly different from that in normal tissues (p = 0.0255)." (PMID 37509501, 2023).
lung adenocarcinoma (continued). "Through statistical analysis of the data, for the lung adenocarcinoma patients with positive RBM10 expression, the survival prognosis and drug sensitivity of the lung adenocarcinoma patients showed statistically significant differences." (PMID 37509501, 2023). "We identified RBM10 as a tumor suppressor gene through database screening and PCR assays, and it plays a negative regulatory role in the occurrence and development of lung adenocarcinoma." (PMID 37509501, 2023). "Nucleic acids were extracted at low temperatures, and qRT-PCR was used to verify the expression levels of the mRNA of RBM10 in lung adenocarcinoma tissues and normal tissues (p < 0.05)." (PMID 37509501, 2023). "RNA-binding motif protein 10 (RBM10) inhibits cell proliferation in lung adenocarcinoma by suppressing EPAC/Rap1/AKT/CREB signalling." (PMID 35011543, 2022). "RNA-binding motif protein 10 (RBM10) is a type of RBP located in the nucleus, which is frequently mutated in various types of cancers, especially lung adenocarcinoma (LA)." (PMID 36335386, 2022). "We also verify that downregulation of RBM10 enhances the malignant phenotype of lung adenocarcinoma cells using in vitro cell experiments, and in vivo animal experiments show that the overexpression of RBM10 reduces the growth of tumors." (PMID 39282149, 2022). "In our study, we first substantiated that RBM10 inhibits the EMT process of lung adenocarcinoma at least partly through negatively regulating the Wnt/β-catenin pathway." (PMID 34975322, 2022). "Mutations are also found in the spliceosomal RNA-binding protein RBM10, in 5–7% of lung adenocarcinomas." (PMID 34065983, 2021). "RBM10 decreases the activation of RAP1 and reduces the phosphorylation of CREB via the AKT signalling pathway, suggesting that RBM10 exhibits its effect on lung adenocarcinoma cell proliferation via the RAP1/AKT/CREB signalling pathway." (PMID 34804951, 2021). "In lung adenocarcinoma, splice regulator RBM10 inhibits tumor cell proliferation and Notch signaling activity." (PMID 33488680, 2020). "RNA-binding motif protein 10 (RBM10) is a regulator of alternative splicing in lung adenocarcinoma; and human antigen R (HuR) promotes cell dedifferentiation and proliferation by regulating the stability of target mRNAs in hepatocellular carcinoma." (PMID 33193718, 2020). "Herein, we assessed the involvement of RBM10 in lung adenocarcinoma cell proliferation and explored the potential molecular mechanism." (PMID 30955253, 2019). "To conclude, this study found that RBM10 inhibits lung adenocarcinoma cell growth in vitro and in vivo." (PMID 30955253, 2019). "We found that, both in vitro and in vivo, RBM10 overexpression suppresses lung adenocarcinoma cell proliferation, while its knockdown enhances cell proliferation." (PMID 30955253, 2019). "There is a correlation between RBM10 expression and survival in lung adenocarcinoma patients." (PMID 40740233, 2025). "An immunohistochemical test was performed on the samples of 20 patients with lung adenocarcinoma in the subcomponent analysis of immune cells, and the protein expression of RBM10 in lung adenocarcinoma tissues was verified by cellular immunofluorescence assays." (PMID 37509501, 2023). "RBM10 mRNA levels were significantly decreased in lung adenocarcinoma A549 cells." (PMID 37509501, 2023). "As a new potential tumor-related biomarker, whether RBM10 can provide us with new means and strategies for the early diagnosis, targeted drug therapy, and curative effect prediction of lung adenocarcinoma remains to be studied." (PMID 37509501, 2023).
lung adenocarcinoma (continued). "Immunohistochemistry analysis and cell immunofluorescence staining also confirmed that RBM10 was involved in the immune regulation of lung adenocarcinoma tissues, and the number of immune cell aggregations was significantly higher than that of the control group." (PMID 37509501, 2023). "The results suggest that the expression of the RBM10 protein in lung adenocarcinoma tissue decreased, which may be related to the negative regulation of the occurrence and development of lung adenocarcinoma." (PMID 37509501, 2023). "In addition to exploring the function and mechanism of RBM10 in the progression of lung adenocarcinoma, this study also focused on exploring the immune regulation mechanism of RBM10 and its influence on the sensitivity of targeted therapy drugs." (PMID 37509501, 2023). "Finally, this study confirmed the inhibitory effect of RBM10 on cell proliferation and metastasis of lung adenocarcinoma." (PMID 39282149, 2022). "Western blotting revealed that the expression of phospho‐AKT and phospho‐CREB was remarkably changed in RBM10‐inoculated tumour tissues.These results indicate that RBM10 functions as a tumour‐suppressing molecule and negatively regulates lung adenocarcinoma cell growth in vivo." (PMID 30955253, 2019). "Our observations may help to better understand how deregulation of RBM10 contributes to lung adenocarcinoma progression." (PMID 30955253, 2019). "In another lung study, a mutation - caused by a T to A substitution and consequent valine (V) to glutamic acid (E) substitution within the second RRM (RRM2) of RBM10 - was reported in A549 lung adenocarcinoma cells, with consequences for NUMB alternative splicing." (PMID 25889998, 2015). "Given the frequent observation of splicing deregulation in different types of cancers, it is plausible that RBM10 might also play an important role in cancers other than lung adenocarcinomas." (PMID 24000153, 2013). "Finally, the PCR results of RBM10 in cancer tissues and adjacent tissues of 20 clinical patients with lung adenocarcinoma were further compared for verification, supporting the conclusion that RBM10 has a negative regulatory effect on the survival and prognosis of lung adenocarcinoma." (PMID 37509501, 2023). "Therefore, these pieces of evidence strongly suggest that RBM10 may inhibit the progression of lung adenocarcinoma by regulating the expression of PD-L1." (PMID 39282149, 2022). "In lung adenocarcinoma (LUAD), RBM10 decreases cell proliferation through inhibiting RAP1/AKT/CREB pathway." (PMID 39282149, 2022). "We found that RBM10 reduces the phosphorylation of CREB via the AKT signalling pathway, suggesting that RBM10 exhibits its effect on lung adenocarcinoma cell proliferation via the RAP1/AKT/CREB signalling pathway." (PMID 30955253, 2019). "Additional significant interaction was identified between KRAS and Protein Tyrosine Phosphatase Receptor Type D (PTPRD), RNA-Binding Motif Protein 10 (RBM10), and Neurogenic locus notch homolog protein (NOTCH1/2/3), reflecting novel immune-related mechanisms in KRAS-mutant lung adenocarcinomas." (PMID 40723270, 2025). "Together with the results presented above, these findings suggest that RBM10 suppresses the phosphorylation of AKT and consequently decreases the expression of CREB, which is involved in the regulation of cell proliferation in lung adenocarcinoma cells." (PMID 30955253, 2019).
TARP syndrome (14 papers, 2013 to 2025). "Our data align with reports showing RBM10 mutations cause TARP syndrome, which affects heart, brain, and limb development." (PMID 40740233, 2025). "Mutations in the RBM10 gene are closely linked to TARP syndrome, highlighting its pivotal role in various cancers." (PMID 40740233, 2025). "Unlike other studies showing various heart conditions and brain abnormalities associated with TARP syndrome, we found this RBM10 variant was associated with severe coagulopathy and pulmonary arteriovenous malformation." (PMID 35991558, 2022). "RBM10 has been recently characterized as a new member of splicing factors, and associated with lung cancer and congenital disorders, such as the TARP syndrome and XLMR." (PMID 33468217, 2021). "In this study, we identified a fission yeast homologue of human splicing factor RBM10, which has been linked to TARP syndrome." (PMID 33468217, 2021). "Several splicing factors displayed higher relative expression in the early mesenchyme, including Rbm10, an AS factor mutated in human TARP Syndrome." (PMID 33013468, 2020). "Interest in RBM10 is rapidly increasing and its clinical importance is highlighted by its identification as the causative agent of TARP syndrome, a developmental condition that significantly impacts affected children." (PMID 29274279, 2018). "For instance, mutations in RBM10 are the cause of TARP syndrome, which results in many developmental abnormalities and often lethality before or soon after birth." (PMID 28662214, 2017). "Mutations in RBM10 are associated with TARP syndrome, an X-linked recessive disorder originally described with cardinal features of talipes equinovarus, atrial septal defect, Robin sequence, and persistent left superior vena cava." (PMID 28577551, 2017). "Mutations in RBM10, which maps to the X chromosome, are associated with TARP syndrome, lung and pancreatic cancers." (PMID 25889998, 2015). "Mutations in RBM10 have been noted in cells associated with lung and pancreatic cancers and the neuromuscular disorder TARP syndrome." (PMID 25889998, 2015). "In the blood cells of patients with TARP syndrome, six different mutations were identified, and a six exon-spanning deletion (aa 651–889) that codes for a truncated RBM10 isoform with an inability to regulate alternative splicing." (PMID 25889998, 2015). "Mutations in RBM10 are known to cause multiple congenital anomaly syndrome in male humans, the TARP syndrome." (PMID 24000153, 2013). "Nonsense and frame shift mutations in RBM10, a gene encoding an RBPs, have been identified to cause TARP syndrome." (PMID 24000153, 2013). "To conclude, we identified a RBM10 variant associated with TARP syndrome." (PMID 35991558, 2022). "TARP syndrome is a rare X-linked genetic condition caused by mutations in the RBM10 gene." (PMID 35991558, 2022). "TARP syndrome (TARP) is caused by mutations in RBM10 (OMIM: 311900)." (PMID 36421828, 2022). "TARP syndrome is caused by loss-of-function mutations in the RBM10 gene." (PMID 35991558, 2022). "In other instances, such RBPs are involved in AS, such as RBM10 which is mutated in TARP syndrome." (PMID 33013468, 2020). "The findings we report here suggest that TARP syndrome might be associated with not only dysfunctional RBM10 but elevated levels of either or both isoforms of SMN2." (PMID 28728573, 2017). "Changes in alternative splicing of the pre-mRNA from key target genes may be how mutated RBM10 contributes to TARP syndrome." (PMID 28728573, 2017). "Mutations in RBM10 cause the TARP syndrome with multiple congenital anomalies." (PMID 26468954, 2015). "Nonsense and frame shift mutations in RBM10 have been identified to be causative for TARP syndrome (Talipes equinovarus, atrial septal defect, Robin sequence and persistent left superior vena cava, MIM #311900), an X-linked inherited disorder leading to multiple organ malformation in affected males." (PMID 24000153, 2013).
TARP syndrome (continued). "Nonsense and frame-shift mutations in RBM10 have been identified to be causative for TARP syndrome." (PMID 24000153, 2013). "Indeed, among the genes with splicing pattern regulated by RBM10, some have been implicated in the TARP syndrome associated anomalies." (PMID 24000153, 2013). "Nonsense and frame-shift mutations in RBM10 have been identified to cause TARP syndrome." (PMID 24000153, 2013). "The impact of RBM10 on various cancer types and TARP syndrome has been extensively studied in recent years, and its role in viral infections is becoming increasingly evident." (PMID 40742131, 2025). "Newly reported cases identified a few novel RBM10 variants and atypical manifestations associated with TARP syndrome, thus expanding the genetic and clinical spectrum of TARP syndrome." (PMID 35991558, 2022). "Herein, we report a previously undiagnosed neonatal patient with a poor prognosis, who was identified to have a hemizygous RBM10 alteration detected by DES establishing a molecular genetic diagnosis of TARP syndrome." (PMID 28577551, 2017). "Whole-mount in situ expression analysis of the murine Rbm10 has shown that the gene was expressed during embryonic development in a pattern consistent with the human malformations observed in TARP syndrome." (PMID 24000153, 2013). "The role played by RBM10 in TARP syndrome is unknown, but likely involves its ability to function as a splicing regulator." (PMID 28728573, 2017). "Furthermore, in a patient suffering from TARP syndrome, we identified an in-frame deletion in RBM10 and demonstrated that the splicing defects in the lymphoblastoid cells derived from the patient were largely due to the loss of nuclear function of RBM10." (PMID 24000153, 2013). "TARP syndrome (TARPS; OMIM 311900) is caused by hemizygous mutation in RBM10." (PMID 34564083, 2021). "Since SMNFL is also involved in RNA processing, the relationship between RBM10 downregulation, increased production of SMNFL and RNA processing in both TARP syndrome and SMA warrants further investigation." (PMID 28728573, 2017). "The usefulness of our findings, with regards to SMA, would depend on the identification of an RBM10 antagonist that could specifically target motor neurons important to SMA, since downregulation of RBM10 (particularly during embryonic development) is the causative agent for TARP syndrome." (PMID 28728573, 2017).